CDK1 (cyclin dependent kinase 1)
Diseases named in the same sentence as CDK1 in open-access papers (continued):
Sharing a sentence is not in itself a finding about the gene and the disease.
metastatic disease (4 papers, 2015 to 2024). "We also validated by immunohistochemistry (IHC) higher CDK1 protein levels in the nucleus of primary metastatic tumors, which were correlated with CDK1 gene expression." (PMID 36854674, 2023).
oral cancer (4 papers, 2016 to 2025). "Moreover, apigenin can induce the apoptosis of tongue and oral carcinoma-derived cell line SCC-25 and regulate the expression of cyclin D and E, inactivation of cyclin dependent kinase 1 (CDK1), and cell cycle arrest at the G0/G and G2/M phases." (PMID 38611874, 2024). "The CDK1 protein overexpression in OSCC was also shown in Xin Chen group, who had shown the presence of CDK1 protein in non-cancer epithelium in 35 % of OSCC cases and in 67.5 % of oral cancer samples." (PMID 26912061, 2016).
teratoma (4 papers, 2017 to 2025). A non-seminomatous germ cell tumor characterized by the presence of various tissues which correspond to the different germinal layers (endoderm, mesoderm, and ectoderm). "Although miR-138-5p and miR-200b-3p have been previously implicated in regulating oncogenes like MYD88 and CDK1 in various cancers, our study provides the first comprehensive analysis of these miRNAs in seminoma and teratoma." (PMID 40869426, 2025). "Similarly, the miRNA regulatory network associated with teratoma hub genes demonstrates distinct miRNA clusters targeting essential oncogenic regulators such as CDK1, HSP90AA1, HSPA4, TRIM28, and TOP2A." (PMID 40869426, 2025). "A direct and experimentally validated interaction also exists between CDK1 and hsa-miR-200b-3p in teratoma, further reinforcing the involvement of this miRNA in teratoma tumorigenesis." (PMID 40869426, 2025). "In teratoma, hsa-miR-200b-3p prominently targets CDK1 and other key oncogenes, exerting control over PI3K/AKT, MAPK/ERK, Wnt/β-catenin, and Hippo signaling." (PMID 40869426, 2025). "Conversely, the teratoma network was dominated by CDK1, HSP90AA1, TRIM28, and TOP2A—genes critically involved in mitotic progression, chromatin remodeling, and cellular stress response." (PMID 40869426, 2025). "Key genes such as CDK1 occupy central positions within these clusters, emphasizing the widespread regulatory influence of hsa-miR-200b-3p in teratoma tumorigenesis." (PMID 40869426, 2025). "In testicular germ cell tumor tissues (germ cell neoplasia in situ, seminomas, ECs, teratomas, mixed non-seminomas) and normal testis tissue, a high expression of CDK1/4/7 and 9 was observed." (PMID 35406461, 2022).
adenoma (3 papers, 2022). A neoplasm arising from the epithelium. "We showed that genes ANLN, CDK1, ECT2, and TNC were associated with adenoma progression to carcinoma, ANLN and PDGFD with development of metastases, while genes ANLN, CDK1, ECT2, and PDGFD were associated with the level of malignancy." (PMID 36362041, 2022). "Similarly, we identified CDK1 upregulation in adenomas with early carcinomas and when compared to adenomas." (PMID 36362041, 2022). "ANLN, CDK1, ECT2, and TNC were differentially expressed between adenoma and adenoma with early carcinoma." (PMID 36362041, 2022). "In adenomas with early carcinomas, statistically significant results include TNXB with 7.7-fold downregulation (p ≤ 0.001), 4.4-fold upregulation of CDK1 (p ≤ 0.01), 14.1-fold upregulation of ANLN (p ≤ 0.001), and 26.3-fold upregulation of ECT2 (p ≤ 0.001)." (PMID 36362041, 2022). "We identified statistically significant differences between the adenoma and adenoma with early carcinoma for ANLN (p ≤ 0.001), CDK1 (p ≤ 0.05), ECT2 (p ≤ 0.01), and TNC (p ≤ 0.05)." (PMID 36362041, 2022). "The genes TNC, CDK1, ANLN, and ECT2 were significantly upregulated in adenoma with early carcinoma when compared to adenoma and can be considered as potential biomarkers for malignant transformation." (PMID 36362041, 2022). "CDK1 was identified as expressed in adenomas and CRC, while expression of its partner CDKN1A was absent, suggesting that the proliferative activity of CRC, which may be an early event in carcinogenesis, is not solely dependent on control of the cell cycle by these two genes." (PMID 36362041, 2022).
Alzheimer disease (3 papers, 2016 to 2026). A progressive, neurodegenerative disease characterized by loss of function and death of nerve cells in several areas of the brain leading to loss of cognitive function such as memory and language. "Aristolactams AII, BII, and velutinam were evaluated for their ability to inhibit DYRK1A and CDK1/cyclin B kinases, that are related with neurodegenerative disorders, like Alzheimer's disease." (PMID 41494962, 2026). "Studies have indicated that circRS-7 acts as an miR-7 sponge in Alzheimer’s disease and Parkinson’s disease, thereby modulating the expression of downstream genes such as cyclin B1 (G2/mitotic-specific) and CdK1 (cyclin-dependent kinase 1), which suppresses cell proliferation and cell migration." (PMID 37508574, 2023). "In this study, we observed that Ad-RAD50 infection decreased the phosphorylation of cdc25c and cdk1." (PMID 26951044, 2016).
anaplastic thyroid cancer (3 papers, 2021 to 2025). "Several studies also determined CDK1 as a key gene in anaplastic thyroid cancer by bioinformatics analysis 43-45." (PMID 35517403, 2022). "Conversely, excessive iodine intake may contribute to the development of papillary and anaplastic thyroid cancer by activating the AKT/Wee1/CDK1 signaling pathway, which accelerates the cell cycle and may contribute carcinogenesis." (PMID 41228194, 2025). "Furthermore, activating AKT/Wee1/CDK1 axis was involved in the proliferation of papillary and anaplastic thyroid cancer cells induced by high iodine." (PMID 33796458, 2021).
atherosclerosis (3 papers, 2019 to 2024). A disease characterized by the build-up of fatty material and calcium deposition in the arterial wall resulting in partial or complete occlusion of the arterial lumen. "The conclusion of these results is: miR-378a-5p/CDK1/p21 is a considerable pathway that can be used as a new therapeutic target in the prevention of atherosclerosis and stent restenosis." (PMID 30838018, 2019).
carcinoid (3 papers, 2009 to 2015). "A study on Bon-1 carcinoid cells showed that PDCD4 not only suppressed the transcription of the mitosis-promoting factor cyclin-dependent kinase 1(CDK1)/cdc2, but also decreased the expression of CDK4/6." (PMID 19480673, 2009). "ASCL1 (p = 0.0016), BCL2 (p < 0.0001), CASP8 (p = 0.0030), CCNE1 (p = 0.0135), CDK1 (p = 0.0146), CDK2 (p = 0.0114), CDKN1A (p = 0.0107) and CDKN2A (p = 0.0002) showed lower expression in carcinoids compared to carcinomas." (PMID 26008974, 2015).
Fanconi anemia (3 papers, 2013 to 2024). Fanconi anemia (FA) is a hereditary DNA repair disorder characterized by progressive pancytopenia with bone marrow failure, variable congenital malformations and predisposition to develop hematological or solid tumors.
female infertility (3 papers, 2019 to 2023). Diminished or absent ability of a female to achieve conception. "Cdk1 and Cdk2 expression has been observed in mouse oocytes, and oocyte-specific deletion of Cdk1 and Cdk2 showed that only the loss of Cdk1 prevents the resumption of meiosis in oocytes, leading to female infertility." (PMID 37686466, 2023). "Additionally, Cdk1 cKO oocytes lead to female infertility as the oocytes are unable to resume meiosis, with a microinjection of Cdk1 rescuing the phenotype, thus confirming the necessity of Cdk1 in mouse female fertility." (PMID 32731332, 2020). "Furthermore, Cdk1 KO, but not Cdk2, resulted in female infertility due to a failure in the resumption of meiosis in oocytes." (PMID 30913540, 2019).
germ cell tumor (3 papers, 2015 to 2022). A benign or malignant, gonadal or extragonadal neoplasm that originates from germ cells. "Elevated expression of cyclin A2 and their catalytic partners CDK1 and CDK2 have been detected in male germ cell tumors, and their levels are quantitatively associated with tumor invasiveness." (PMID 25782154, 2015).
Hyperglycemia (3 papers, 2020 to 2025). An increased concentration of glucose in the blood. "Furthermore, FOXO1 is already active in young Cdk1 cKO mice, exacerbating hyperglycemia via gluconeogenesis." (PMID 33345777, 2020). "Cyclin-dependent kinase 1 (Cdk1) and PKC-δ, which are increased in hyperglycaemia, played a critical role in ROS-driven phosphorylation of DRP1 Ser616 residue, promoting mitochondrial fission and cardiomyocyte death." (PMID 40243689, 2025).
Insulin resistance (3 papers, 2020 to 2025). Increased resistance towards insulin, that is, diminished effectiveness of insulin in reducing blood glucose levels. "In preclinical models, the loss of CDK1 reduces cell proliferation and lipid metabolism, which results in insulin resistance." (PMID 39865653, 2025). "As a result, aged Cdk1 cKO mice develop hepatic insulin resistance, likely through reduced INSRB expression and reduced insulin receptor auto-phosphorylation." (PMID 33345777, 2020). "The development of insulin resistance in aged Cdk1 cKO mice is supported by our observation of reduced insulin signaling, increased blood glucose levels, reduced glucose tolerance, and diminished response to insulin." (PMID 33345777, 2020). "Taken together, aged Cdk1 cKO mice develop insulin resistance, possibly due to chronic hyperinsulinemia." (PMID 33345777, 2020). "Chronic hyperinsulinemia can lead to insulin resistance in patients, hence we wondered whether plasma insulin remained high in Cdk1 cKO mice over time." (PMID 33345777, 2020). "We provide a potential mechanistic pathway by which senescence can lead to steatosis, through inhibition of CDK1 activity, eventually leading to FFA-induced chronic hyperinsulinemia and the consequent insulin resistance." (PMID 33345777, 2020).
ischemic stroke (3 papers, 2021 to 2022). A stroke disorder caused by obstruction of blood flow to the brain, due to thrombotic (local blood clot formation) or embolic (due to a blood clot or other material traveling from another site) event. "Finally, comprehensive analysis of the results identified the miR-425-5p-Cdk1, mmu-miR-1186b-Prc1, mmu-miR-434-3p-Prc1, and mmu-miR-453-Prc1 miRNA–mRNA networks as key networks that are regulated by EA and linked to ischemic stroke." (PMID 34566862, 2021). "Cdk1,Ccnb,and Cdc20, the members of module-A networks with the highest degrees, possess the potential of being biomarkers of ischemic stroke due to their function in the cell cycle." (PMID 35485294, 2022). "There is in vitro and in vivo evidence for involvement of CDKs in neuronal death after ischemic stroke, including CDK1, -2, -5, and -7 but also cyclins and other CDKs binding partners." (PMID 33429982, 2021). "Specific inhibition of either CDK1 or CDK5 showed a beneficial effect on neurological score following ischemic stroke." (PMID 33429982, 2021). "Ultimately, seven downregulated hub genes (including Mki67, Cdk1, Tpx2, Cenpf, Ccnb2, Prc1, and Top2a) were identified as key genes regulated by EA treatment in ischemic stroke by PCR validation." (PMID 34566862, 2021). "CDK1 and CDK5 are associated with detrimental effect on infarct size following ischemic stroke." (PMID 33429982, 2021). "Overall, key miRNA-mRNA networks were identified based on RNA-seq and RT-qPCR validations, and we found that miR-425-5p-Cdk1, mmu-miR-1186b-Prc1, mmu-miR-434-3p- Prc1, and mmu-miR-453-Prc1 were crucial networks regulated by EA in brain neuronal cells of ischemic stroke." (PMID 34566862, 2021).
kidney cancer (3 papers, 2018 to 2023). Primary or metastatic malignant neoplasm involving the kidney. "Another study showed that miR-31-5p acts as a tumor suppressor in kidney cancer by targeting CDK1 and constraining proliferation, migration, invasion and cell cycle." (PMID 37047552, 2023). "Examination of the expression of cell cycle genes across cancer types revealed that several kidney cancer samples had lower CDK1 levels when compared to their matched normal parts." (PMID 29843367, 2018). "Taken together, besides RNASEH2A upregulation, the CD151-related pathway might contribute to tumor growth in CDK1-low kidney cancers." (PMID 29843367, 2018). "In search of an alternative pathway that promotes tumor proliferation, we performed gene correlation studies in five kidney cancer patient samples with high RNASEH2A expression, low CDK1 expression, and bad clinical outcomes (death)." (PMID 29843367, 2018).
leiomyosarcoma (3 papers, 2019 to 2025). An uncommon, aggressive malignant smooth muscle neoplasm, usually occurring in post-menopausal women. "Two members of the retinoblastoma pathway, TOP2A and CDK1, were further shown as potential diagnostic biomarkers to distinguish leiomyomas from leiomyosarcomas and as prognostic tools in leiomyosarcoma patients." (PMID 41162745, 2025). "Both TOP2A and CDK1 were among the top 25 differentially expressed genes and were overexpressed in leiomyosarcomas." (PMID 41162745, 2025). "Previous array-based expression studies have shown that TOP2A and CDK1 are overexpressed in leiomyosarcomas when compared to leiomyomas." (PMID 41162745, 2025). "Our results indicate both TOP2A and CDK1 as potential prognostic biomarkers in uterine leiomyosarcomas." (PMID 41162745, 2025). "Notably, high expression of both TOP2A and CDK1 independently predicted worse survival in uterine leiomyosarcoma patients at all stages." (PMID 41162745, 2025). "Similarly, a considerable proportion of leiomyosarcomas showed high or moderate CDK1 protein expression (44/56; 79%), while most leiomyomas displayed low expression (49/65; 75%)." (PMID 41162745, 2025). "CDK1 expression has not been previously assessed as a prognostic indicator in uterine leiomyosarcomas." (PMID 41162745, 2025).
liver fibrosis (3 papers, 2020 to 2025). "The high expression of CDK1, a key regulator of cell cycle G2/M turnover, in liver fibrosis HCC suggests its important role in promoting tumor cell proliferation and inhibiting apoptosis." (PMID 40332418, 2025). "In this study, we deeply explored the biological role of CDK1 in liver fibrosis and liver CC, revealing its central position in cell cycle regulation and its potential value as a therapeutic target." (PMID 40332418, 2025). "In conclusion, in this study, we deeply explored the use of the expression pattern, biological function, and its possibility as a potential biomarker of CDK1 in liver fibrosis and liver CC." (PMID 40332418, 2025). "In terms of clinical application, the expression level of CDK1 can be used as a basis for personalized treatment of patients with liver fibrosis." (PMID 40332418, 2025). "Our results not only confirm the multiple biological functions of CDK1 in liver fibrosis and liver CC, but also provide a rationale for CDK1-based targeted therapy." (PMID 40332418, 2025). "The interdisciplinary research approach will combine molecular biology, cell biology, bioinformatics, modern biological technology, and clinical medicine, to deeply analyze the specific mechanism of action of CDK1 in the process of liver fibrosis." (PMID 40332418, 2025). "CDK1 plays an important role in the activation and proliferation of hepatic stellate cells (HSCs) by regulating liver fibrosis." (PMID 40332418, 2025). "We used microarray comparison to analyze the gene expression profiles of human growth and aging-activated HSCs and found that CDK1 gene expression was positively correlated with the occurrence of liver fibrosis." (PMID 40332418, 2025). "Further, this study not only deepens our understanding of the role of CDK1 in liver fibrosis HCC at the theoretical level, but also provides new tools and strategies for the precise treatment and prognosis evaluation of HCC at the practical level." (PMID 40332418, 2025). "Immune infiltration analysis, through algorithms, such as CIBERSORT and TIMER, allowed us to gain insight into the role of CDK1 in the tumor microenvironment, especially the influence on immune cell infiltration related to liver fibrosis." (PMID 40332418, 2025). "Therefore, based on the logical reliability analysis, we identified CDK1 as a new key target for the treatment of liver fibrosis." (PMID 40332418, 2025). "Therefore, future studies should combine more clinical data and experimental validation to provide a more comprehensive understanding of the mechanism of CDK1 action in liver fibrosis and HCC." (PMID 40332418, 2025). "CDK1 is the most likely critical target for the treatment of liver fibrosis." (PMID 40332418, 2025). "When exploring the clinical application of CDK1 as a biomarker for liver fibrosis, we must first recognize its central role in cell cycle regulation, which is not only widely recognized in basic biological studies, but also gradually shows its importance in clinical pathology." (PMID 40332418, 2025). "It was shown that inhibition of CDK1 activity can downregulate the proliferation of HSCs and reduce ECM synthesis, thereby inhibiting the progression of liver fibrosis." (PMID 40332418, 2025). "Therefore, we also probed whether aged Cdk1 cKO mice develop liver fibrosis." (PMID 33345777, 2020). "However, although we clarified that CDK1 plays a role in the treatment of liver fibrosis, the location of action, pathways, and mechanisms of CDK1 in the treatment of liver fibrosis are not clear." (PMID 40332418, 2025). "Despite the lack of an inflammatory response, liver fibrosis in aged Cdk1 cKO mice could still be induced by factors released by steatotic hepatocytes that are sufficient to activate the fibrogenic hepatic stellate cells." (PMID 33345777, 2020).
microcephaly (3 papers, 2019 to 2025). A congenital or acquired developmental disorder in which the circumference of the head is smaller than normal for the person's age and sex. "Microcephalin-1 (MCPH1) exists as 2 isoforms that regulate cyclin-dependent kinase-1 activation and chromosome condensation during mitosis, with MCPH1 mutations causing primary microcephaly." (PMID 30303738, 2019). "Since the UFM1 cascade regulates cell cycle progression at the entry into mitosis, certain chemicals or drugs targeting CDK1 could be used to address microcephaly phenotypes, as observed in the case of HLD14." (PMID 39846712, 2025).
ovarian tumors (3 papers, 2016 to 2025). "Cyclin dependent kinase 1 (Ccnd1) was downregulated in response to E2 and altered in 8 % of ovarian tumors." (PMID 26879975, 2016). "Furthermore, miR-490-3P targets CDK1 and restrains the growth of ovarian tumors." (PMID 39991589, 2025). "The differences of CDC25C (P = 0.000), pCDC25CSer216 (P = 0.001), CDK1 (P = 0.000), CHK1 (P = 0.000), CHK2 (P = 0.000), PLK1 (P = 0.000) and Aurora A (P = 0.000) expression had statistical significances among these ovarian tumor groups." (PMID 32393310, 2020).
prostate adenocarcinoma (3 papers, 2020 to 2024). "Paradoxically, FOXO1 has also been found to be activated by CDK1 to induce apoptosis gene activation in post-mitotic neurons but FOXO1 phosphorylation by CDK1 promotes its inhibition in human prostate adenocarcinoma cells." (PMID 32372224, 2020). "A differential survival analysis carried out with GEPIA showed the correlation of ZWINT, CDK1, IGFPB3, and TYMS expression with disease-free survival (DFS) in a database of patients with prostate adenocarcinoma." (PMID 38542079, 2024).